INS (insulin)
Diseases named in the same sentence as INS in open-access papers (continued):
Sharing a sentence is not in itself a finding about the gene and the disease.
Insulin resistance (continued). "Moreover, we observed an increase in insulin levels during glucose tolerance test, confirming insulin resistance." (PMID 30979946, 2019). "The first 30 min of OGTT is deeply related to the early stages of insulin reaction, and is called the “first phase insulin release”, which is an indicator as to whether insulin resistance or type 2 diabetes will develop." (PMID 31212747, 2019). "Among those, insulin signaling and insulin resistance has been shown to promote training of cells that may partly explain altered responses and pathologies associated with obesity and insulin resistance." (PMID 31244863, 2019). "More recent data from a large cross-sectional study in Denmark suggest a ‘U-shaped’ association between IGF-I serum concentrations and insulin sensitivity, as both low and high IGF-I levels were related to insulin resistance, when compared to subjects with intermediate IGF-I levels." (PMID 30392760, 2019). "However, under the situation of insulin resistance, and once the β-cells become unable to release sufficient insulin, glucose concentrations will increase." (PMID 30678216, 2019). "The marked and sustained improvements in our cohort could be explained by the effects of a low carbohydrate diet on insulin action in T2D and IGT patients, where insulin levels are high and insulin resistance marked." (PMID 31357547, 2019). "In addition, reactive species by impairing glucose uptake in muscle and fat, and also by reducing insulin secretion from pancreatic β cells play a crucial role in insulin resistance." (PMID 31163689, 2019). "“Brain insulin resistance” could be due to either impaired response of brain cells to the extracellular insulin or disrupted transport of insulin to the brain." (PMID 30975165, 2019). "In addition, studies have shown that H. pylori can promote insulin resistance by inducing chronic inflammation and affecting insulin regulation of gastrointestinal hormones." (PMID 31583248, 2019). "It is well-known that TSH and insulin are involved in thyrocyte proliferation, and several studies have reported that patients with insulin resistance might have large thyroid volumes and a higher prevalence of TNs." (PMID 31379740, 2019). "This study did not measure plasma insulin concentrations which would have enabled the authors explore associations with insulin resistance." (PMID 30944035, 2019). "Our study has demonstrated a positive relationship between intake of stearic acid (C18:0) and insulin resistance, and a negative association between intake of lauric acid (C12:0) and fasting insulin secretion." (PMID 30871233, 2019). "This is may be due to progressive impairment of insulin secretion with time by ß- cell and increase in insulin resistance and a sudden decrease in insulin secretion." (PMID 31464602, 2019). "In addition, this study demonstrated that probiotic consumption reduced insulin levels and insulin resistance and enhanced insulin sensitivity compared with placebo." (PMID 31450864, 2019). "Damage to the hepatic insulin signaling pathway can lead to insulin resistance." (PMID 31555134, 2019). "Furthermore, insulin resistance was mainly defined by insulin [model 2: loading = 0.66, p < 0.001; model 3: loading = 0.72, p < 0.001], and obesity by BMI [model 2: loading = 0.85, p < 0.001; model 3: loading = 0.83, p < 0.001]." (PMID 31801522, 2019). "Similarly, a research in endothelin-1 (ET-1) has emphasized the use of ET-1 treatment resulted in heterologous desensitization of insulin signalling, defined as chronic ET-1-induced cellular insulin resistance." (PMID 30621321, 2019). "Another study also demonstrated that there is a positive association between SAA and insulin sensitivity and that an increase SAA level could result in insulin resistance in human adipose tissues, which was consistent with our findings." (PMID 31060494, 2019).
Insulin resistance (continued). "Glucose levels decreased later after insulin administration; thus, a slight insulin resistance which may decrease eNOS activity." (PMID 30717220, 2019). "In our study, the negative correlation of irisin with markers of insulin resistance indicated that decreased irisin expression in response to decreasing insulin sensitivity and disturbance in metabolisms associated with obesity." (PMID 31881940, 2019). "Other factors, such as glucose, insulin, cytokines, ghrelin, leptin, and other indices of insulin resistance may also participate in the abnormal lipid metabolism in diabetic patients." (PMID 31010439, 2019). "Risk alleles like FTO, ADIPOQ, INSR, IRS1, IRS2, PPARG, CAPN10 may leave individuals more vulnerable to insulin resistance and/or adiposity (which can result in peripheral insulin resistance), leading to high circulating insulin." (PMID 31367382, 2019). "We tested our flies for insulin resistance by testing their response to injected human insulin." (PMID 30910908, 2019). "Low circulating Mg levels and T2DM are known to be related, mainly through insulin resistance rather than through insulin secretion, but the cause and effect relationships remain to be established." (PMID 30717286, 2019). "Further investigation was carried out to establish the potential mechanisms of insulin resistance in male offspring, through the investigation of mRNA expression of key insulin signalling genes within the target tissues, that is liver, skeletal muscle and adipose tissue." (PMID 31300679, 2019). "There are two types of this disease: type 1, caused by the lack of insulin secretion, and type 2, influenced by insulin resistance." (PMID 31053131, 2019). "Acylcarnitines and “3‐hydroxybutyryl‐carnitine” are associated with insulin resistance, and they may act in synergy with BCAA to suppress insulin actions." (PMID 31724339, 2019). "The absence of the ob gene was associated with insulin resistance, reflected by the increased (P < 0.001) levels of glucose, insulin, and HOMA index as well as by low adiponectin levels." (PMID 30818874, 2019). "Increased flux of FFA level by enhancement of adipose lipolysis mainly leads to TG accumulation via FA esterification in the liver, and then newly synthesized TGs are restored as LDs and secreted as VLDL during obesity and insulin resistance because FFAs also stimulate insulin secretion." (PMID 31208033, 2019). "Kobashi and his colleagues suggested that IL-8 could induce insulin resistance via the inhibition of insulin-induced Akt phosphorylation in adipocytes." (PMID 31407623, 2019). "In order to understand the pathogenesis of insulin resistance it should considered whether, in addition to the impairment of insulin's glucose-lowering action, its other functions are compromised too." (PMID 31214120, 2019). "The elevation of insulin secretion may be compensatory for the increase of insulin resistance in KTRs." (PMID 31252561, 2019). "IFG and IGT are different with respect to the degree of insulin resistance and insulin secretion, and it is possible that serum neopterin concentration may differ between IFG alone, IGT alone, and IFG+IGT together in large study subjects." (PMID 30873113, 2019). "Insulin resistance in peripheral insulin target tissues is important in the pathogenesis of T2D." (PMID 31311313, 2019). "Whereas CO offspring demonstrated a greater glucose response than other groups, suggesting the hepatic insulin resistance could be additive to the gonadal insulin resistance." (PMID 31300679, 2019). "Indeed, saturated FFAs such as palmitate promote skeletal muscle insulin resistance in part by blocking insulin mediated IRS-1 tyrosine phosphorylation and PI3K activity." (PMID 31497027, 2019).
Insulin resistance (continued). "The degree of insulin resistance results in heightened need for insulin production, and glucose levels rise as the resistance exceeds the ability of the pancreatic beta cells to release adequate amounts of insulin, ultimately contributing to risk for Type 2 diabetes." (PMID 31382417, 2019). "The serum concentration of follicle stimulating hormone and the estradiol significantly increased in rats with PCOS, whereas the testosterone and luteinizing hormone concentrations, glucose, insulin, and insulin resistance concentrations significantly decreased during vitamin D treatment (p<0.001)." (PMID 31673465, 2019). "While the role of FFA-stimulated insulin secretion on the progression of insulin resistance is known, we formulated a mathematical model that incorporates FFA-stimulated insulin secretion explicitly and were able to quantify differences in this effect pre- and post-surgery." (PMID 31499737, 2019). "Insulin resistance can occur through dysfunction of insulin signaling pathway." (PMID 30717446, 2019). "Obese rats showed increased levels of fasting plasma glucose, insulin, insulin resistance (homeostatic model assessment-insulin resistance), total cholesterol, low-density lipoprotein cholesterol, inflammatory markers, and leptin compared to those in the control group." (PMID 31284705, 2019). "Insulin resistance (IR) and increased insulin levels are also common in women with PCOS." (PMID 31897389, 2019). "This indicates that insulin resistance may play a key role in the pathogeneses of LADA together with autoimmune destruction of the insulin producing beta-cells." (PMID 30971952, 2019). "Insulin resistance was characterized by a marked decrease in the sensitivity of the body’s glucose metabolism to insulin, a rise in blood sugar, a large amount of insulin, and a high level of insulin in order to maintain normal levels of blood sugar and then cause hyperinsulinemia." (PMID 33817159, 2019). "Therefore, it seems more justified to assess the secondary biochemical parameters of insulin resistance than the insulin concentration level itself." (PMID 31398932, 2019). "Oxidative stress also impairs insulin signaling, which contributes to insulin resistance in T2DM." (PMID 30972029, 2019). "While incompletely understood, insulin resistance may promote tumorigenesis through increased levels of insulin, insulin-like growth factors, and sex steroids and their role in energy intake, increased cellular proliferation, and suppression of apoptosis." (PMID 31781211, 2019). "Fasting blood glucose (FBG) and insulin were used to derive insulin resistance (HOMA-IR)." (PMID 31828076, 2019). "Also, when endogenous production of insulin is compromised (or in state of very high insulin resistance), the role of PE is even more important due to its insulin-independent hypoglycemic effect." (PMID 31644699, 2019). "Elevation of insulin secretion in kidney transplant recipients may be compensatory for increase of insulin resistance." (PMID 31252561, 2019). "Finally, the pubertal PCOS mouse model displayed signs of insulin resistance compared to placebo-treated mice while the adult PCOS mouse model remained insulin sensitive." (PMID 30871463, 2019). "Thus, CB1R signal transduction in peripheral tissues contributes to the development of T2DM through the induction of insulin resistance and impairment of insulin release." (PMID 31035653, 2019). "However, taking into account the glucose/insulin ratio, the 10-month treatment group showed a 30% higher glycaemia per amount of insulin, which is suggestive of insulin resistance." (PMID 31455371, 2019). "Insulin resistance in the brain may also alter the peripheral effects brain insulin has on metabolism." (PMID 31849810, 2019). "Furthermore, elevated SUA harbors a positive correlation with insulin secretion and insulin resistance indexes in newly diagnosed T2DM patients, implying a possible role for SUA in β-cell function." (PMID 30941277, 2019).
Insulin resistance (continued). "Thus, other reports and the present study suggest at least a partial disconnection between reduced mitochondrial oxidation of fatty acids and reductions in skeletal muscle insulin signaling and resultant insulin resistance reported with obesity." (PMID 30935113, 2019). "In other words, elevated levels of blood glucose, insulin, and free fatty acids following a high GI diet can induce insulin resistance, which could lead to increased triglyceride, a greater inflammatory response, and a decrease in HDL cholesterol." (PMID 31336986, 2019). "Furthermore, this treatment induced a reduction of C16:0 ceramides plasma levels, resulting in improved glucose tolerance and insulin sensitivity, confirming the strict correlation between ceramide, obesity and insulin resistance again." (PMID 31771303, 2019). "Indeed, it has been recently found that insulin resistance, the impaired responsiveness to insulin, typical of T2D, occurs in PD brains and plays a key role in the progressive development of PD pathological hallmarks." (PMID 31474827, 2019). "TNF and IL-6 could impair intracellular insulin signalling, potentially leading to insulin resistance." (PMID 31387569, 2019). "Insulin resistance (IR), a subnormal biological response to normal insulin concentrations in target cells (e.g., hepatocytes, skeletal muscle cells, and adipocytes), plays a pivotal role in the development of several metabolic diseases including T2DM, hypertension, and hyperlipidemia." (PMID 32082162, 2019). "The recent Insulin Resistance Intervention After Stroke (IRIS) study included 3876 patients free from type T2DM but insulin resistant according to the homeostasis model assessment of insulin resistance index (HOMA-IR) and with a recent ischemic stroke or transient ischemic attack." (PMID 30805659, 2019). "The improvement of insulin sensitivity may involve mechanisms different from those involved in the decrease in insulin resistance induced by the dietary intervention." (PMID 31635041, 2019). "The role of the microbiota in this increased acetate production of obese/IR states, particularly in the fasted state may be significant and may lead to altered glucose-stimulated insulin production, fat storage and could ultimately lead to insulin resistance." (PMID 30791497, 2019). "It has been demonstrated that patients with insulin resistance (IR) and high serum levels of insulin might have large thyroid volumes and a higher prevalence of thyroid nodules." (PMID 31379740, 2019). "Moreover, we also analyzed data regarding glucose levels after an insulin bolus, and we have calculated the insulin resistance of these mice through the Homeostatic Model Assessment of Insulin Resistance (HOMA-IR)." (PMID 31198829, 2019). "However, although these factors are central triggers initiating the development of cardiac insulin resistance, there are several other pathophysiological processes contributing to impaired myocardial insulin sensitivity." (PMID 30343468, 2019). "Some agents exhibit insulin-resistance-reducing effects and might reduce the requirement for insulin secretagogues such as sulfonylureas and meglitinides." (PMID 31438580, 2019). "The contrasting associations with risk for the beta-cell dysfunction and insulin-resistance SNPs would therefore lend further support for a role of insulin in RCC etiology, as well as explain the lack of association with RCC risk for overall type 2 diabetes." (PMID 30605491, 2019). "Fetal insulin resistance was associated with maternal insulin resistance or insulin sensitivity in non-diabetic pregnancies." (PMID 31849831, 2019). "Plasma insulin concentrations at t0 and t30–t60 minutes and area under the insulin curve following glucose bolus were significantly reduced together with homeostatic model assessment of insulin resistance (SHR, 1.22±0.06, Camk2n1−/−, 0.51±0.06, P=0.00001) in Camk2n1−/− compared with SHR." (PMID 31327268, 2019).
Insulin resistance (continued). "Of the seven papers reviewed, four articles studied insulin level and insulin resistance." (PMID 31817324, 2019). "Two other indexes based on insulin and triglyceride (TG), the McAuley index and body mass index (BMI), and index based on triglyceride, the revised McAuley index, were also used to determine insulin resistance in research/epidemiological studies." (PMID 30866603, 2019). "Moving away from clinical cutoffs of ‘insulin resistance’, and instead considering reduced insulin sensitivity on a continuum might better inform this question." (PMID 31367382, 2019). "Overall, it seems that clinical phenotypes with increased insulin resistance and therefore with high post-prandial insulin, higher BMI, or waist circumference, especially in the presence of diabetes, might benefit the most from the LGI diet." (PMID 31323991, 2019). "Our study also suggests that HDAC4‐mediated FoxO1 deacetylation could represent a novel target for pharmacotherapy, not only of decreasing glucose‐sensitive insulin secretion but also for insulin resistance." (PMID 30968599, 2019). "Finally, the effects of IH on insulin secretion and insulin resistance are elucidated by using an in vitro chamber system that can mimic and manipulate IH." (PMID 31455007, 2019). "In AD, insulin resistance is mainly attributed to defects in insulin downstream post-binding actions that may develop in response to multiple factors, such as the accumulation of Aβ oligomers as well as other stress and inflammatory-related molecules." (PMID 31137621, 2019). "Cav-1 within the endothelium may be crucial in defining insulin uptake into peripheral skeletal muscle where over 80% of glucose uptake occurs and is a potential site for development of insulin resistance." (PMID 31534971, 2019). "Studies in animal and cellular models have also indicated that propolis modulates oxidative stress, the accumulation of advanced glycation end products (AGEs), and adipose tissue inflammation, all of which contribute to insulin resistance or defects in insulin secretion." (PMID 31805752, 2019). "Furthermore, an insulin resistance model was established by exposing cells with palmitate before treatment with well-known antidiabetic drugs, insulin and metformin." (PMID 31048842, 2019). "Insulin resistance (IR) was suspected if the 45-min insulin concentration was > 100 μIU/mL." (PMID 30808423, 2019). "Patients with type 1 diabetes mellitus (T1DM) have traditionally been described as lean and insulin-sensitive subjects, in whom absolute insulin deficiency rather than insulin resistance is the main pathophysiological mechanism behind chronic hyperglycemia." (PMID 30617710, 2019). "We further assess insulin resistance and insulin sensitivity by homeostasis model assessment." (PMID 31019978, 2019). "Besides its well-established role in AD, emerging evidence suggests insulin resistance also occurring in the brain of PD patients pointing to impaired brain insulin signaling as a potential contributing factor to the pathological defects of PD." (PMID 31787891, 2019). "Treatment of HFD fed rats with liraglutide, a GLP-1 receptor agonist with potent anti-inflammatory property, for four weeks fully prevented HFD-induced muscle microvascular insulin resistance, restored small arterial vessel endothelial function, and improved insulin-stimulated glucose disposal." (PMID 30699907, 2019). "An obese child who already has some degree of insulin resistance yet is able to compensate appropriately by increasing insulin section and maintaining euglycemia may somewhat decompensate when entering puberty, where an additional metabolic burden occurs." (PMID 31474943, 2019). "Indeed such low-level chronic inflammation affects the pancreatic production of insulin and triggers the development of insulin resistance, eventually leading to an impaired control of the blood glucose concentration." (PMID 30863457, 2019).